PLP2 (proteolipid protein 2)
Diseases named in the same sentence as PLP2 in open-access papers (continued):
Sharing a sentence is not in itself a finding about the gene and the disease.
tumor (15 papers, 2007 to 2024). "As we expected, high PLP2+ Tumor EPCs score was associated with worse clinical outcome, while low PLP2+ Tumor EPCs score was associated with better clinical outcome (P < 0.0001)." (PMID 38482016, 2024). "Subsequent construction of ROC curves and column charts, along with comprehensive analysis, indicates that a low PLP2+ Tumor EPCs score is associated with a better prognosis, while a high PLP2+ Tumor EPCs score is conversely related to a poorer prognosis." (PMID 38482016, 2024). "The PLP2 missense variant affects a gene that encodes the proteolipid protein 2 playing an important role in different tumor progression (growth and metastasis) because of its capacity to promote the activation of PI3K/Akt pathway." (PMID 36139188, 2022). "The identified missense variant exchanges the encoded amino acid of PLP2 at position 17 (p.Thr17Ile), which is classified as deleterious and affects a protein that plays a role in tumor growth and metastasis." (PMID 36139188, 2022). "Tumour cell GI was associated with downregulation of PLP2 and XCL2 as well as with disruption of the mitotic spindle." (PMID 22134506, 2012). "Recently, PLP2 has been reported to be associated with tumor aggressiveness and poor prognosis." (PMID 32596309, 2020). "The presentation of the subgroups on the CD99 signaling pathway reveals that the C3 PLP2+ Tumor EPCs subgroup has the highest quantity and centralization score, providing evidence of a robust association between this pathway and the C3 PLP2+ Tumor EPCs subgroup." (PMID 38482016, 2024). "Therefore, we hypothesize that the C3 PLP2+ Tumor EPCs subgroup is intricately linked to the progression of the tumor." (PMID 38482016, 2024). "For example, CI.1040, Nutlin.3a, PF.02341066, Metformin, EHT.1864, and LFM.A13 had higher drug sensitivities in high PLP2+ Tumor EPCs group than in low PLP2+ Tumor EPCs score group." (PMID 38482016, 2024). "Immune Score and EATIMATE Score were both low PLP2+ Tumor EPCs score group higher than high PLP2+ Tumor EPCs score group." (PMID 38482016, 2024). "This confirmation underscores the significance of the C3 PLP2+ Tumor EPCs subgroup as the focal point in this study." (PMID 38482016, 2024). "In order to explore the differences between high PLP2+ Tumor EPCs score group and low PLP2+ Tumor EPCs score group, the following analysis was made." (PMID 38482016, 2024). "Compared with low PLP2+ Tumor EPCs score group, the prognosis of high PLP2+ Tumor EPCs score group was worse." (PMID 38482016, 2024). "Next, the nine PLP2+ Tumor EPCs score genes were divided into high PLP2+ Tumor EPCs score group and low PLP2+ Tumor EPCs score group for survival analysis." (PMID 38482016, 2024). "In order to avoid multicollinearity of these genes, lasso regression was used for further screening, and nine genes constituting PLP2+ Tumor EPCs score were selected." (PMID 38482016, 2024). "Visualizing the Tumor Purity of two groups, the value of Tumor Purity of high PLP2+ Tumor EPCs score group was higher." (PMID 38482016, 2024). "In order to explore the immune infiltration of high PLP2+ Tumor EPCs score group and low PLP2+ Tumor EPCs score group, the predicted abundance of different immune cells was displayed." (PMID 38482016, 2024). "In contrast, the low PLP2+ Tumor EPCs score group exhibited a higher prevalence of T cells CD8, regulatory T cells, and naive B cells, mostly associated with favorable prognoses in various cancers." (PMID 38482016, 2024). "Violin diagram showed the interaction between cells, and it was found that the epithelial cell subgroup C3 PLP2+ Tumor EPCs was highly expressed on CD99." (PMID 38482016, 2024). "It was found that ATT6, ERG and PLAGL1 were more expressed in high PLP2+ Tumor EPCs score group, while SPIB was more expressed in low PLP2+ Tumor EPCs score group (P < 0.001)." (PMID 38482016, 2024).
tumor (continued). "The differential expression of genes in high PLP2+ Tumor EPCs score group and low PLP2+ Tumor EPCs score group, and the differential expression in different ages, different T, N, M stages and different races were demonstrated by box plots." (PMID 38482016, 2024). "OS was negatively correlated with PLP2+ Tumor EPCs score, ERG was significantly negatively correlated with JUND, and most other modeling genes were positively correlated." (PMID 38482016, 2024). "PLP2+ Tumor EPCs score was positively correlated with Mast cells activated, Macrophages M0, Dendritic cells activated, and negatively correlated with T cells CD8, T cells regulatory, B cells naive, etc.." (PMID 38482016, 2024). "According to the median PLP2+ Tumor EPCs score, patients in TCGA-CESC cohort were divided into high PLP2+ Tumor EPCs score group and low PLP2+ Tumor EPCs score group." (PMID 38482016, 2024). "To substantiate the role of the C3 PLP2+ Tumor Epithelial Progenitor Cells subgroup in tumor advancement, we proceeded with the development of a novel prognostic model using LASSO regression analysis and COX risk regression analysis." (PMID 38482016, 2024). "The high PLP2+ Tumor EPCs score group was found to have a higher prevalence of activated Mast cells, Macrophages M0, and activated Dendritic cells." (PMID 38482016, 2024). "Based on the median risk score, it has been divided into two distinct prognostic groups: the high PLP2+ Tumor EPCs score group and the low PLP2+ Tumor EPCs score group." (PMID 38482016, 2024). "In subsequent research, we plan to validate the role of the PLP2+ Tumor EPCs score in CC across a larger sample size." (PMID 38482016, 2024). "Analysis of the difference of immune infiltration between high PLP2+ Tumor EPCs score group and low PLP2+ Tumor EPCs score group." (PMID 38482016, 2024). "The PLP2+ Tumor EPCs score of each patient in TCGA-CESC data set was calculated according to the expression level and regression coefficient of nine genes which established the model." (PMID 38482016, 2024). "More recently, the upregulation of miR-765 was described in the plasma of ccRCC patients after tumor resection, suggesting its tumor suppressor role and identifying the proteolipid protein 2 (PLP2) as a candidate downstream target gene." (PMID 37372161, 2023). "Taken together, these results indicate that PLP2 should be a tumor-promoting protein by accelerating cell proliferation, EMT process, invasion and metastasis in UCEC." (PMID 33859750, 2021). "In summary, we have shown that down‐regulation of PLP2 increased ER stress‐induced apoptosis, and cotreatment with an autophagy inhibitor further reduced tumour cell survival in vitro." (PMID 31778016, 2020). "Secondly, PLP2-knockout mice display increased ER stress in neurons under hypoxia, which leads to apoptotic cell death; downregulation of PLP2 increased ER stress-induced apoptosis and reduced tumor cell survival in vitro." (PMID 32596309, 2020). "To assess the function of PLP2 in vivo, we established orthotopic tumour models by implanting U87‐shNC, U87‐shPLP2, U251‐shNC and U251‐shPLP2 cells intracranially into nude mice." (PMID 31778016, 2020). "Among these genes, PLP2 was upregulated and positively associated poorer survival, whereas LYVE1, FABP4, TGFBR3, and FXYD6 were downregulated and identified as tumor suppressor genes." (PMID 31803141, 2019). "It was reported that in BC stem cells, upregulation of miR-422a attenuated microsphere formation, proliferation, and tumor formation via suppressing the PLP2 (Proteolipid protein 2) expression." (PMID 30301470, 2018). "Therefore, the PLP2+ Tumor EPCs score can serve as a theoretical basis for clinical decision-making." (PMID 38482016, 2024). "This analysis identified our targeted subgroup for this study: the C3 PLP2+ Tumor EPCs subgroup." (PMID 38482016, 2024).
tumor (continued). "The cell communication pattern of CD99 signaling pathway was displayed by scatter plot, and it could be seen that the tumor epithelial cell subgroup C3 PLP2+ Tumor EPCs had a large number and the highest intensity on CD99 signaling pathway." (PMID 38482016, 2024). "The constructed PLP2+ Tumor EPCs score has been demonstrated as an independent prognostic factor." (PMID 38482016, 2024). "Based on the analysis of drug sensitivity, it is suggested that heightened sensitivity to drugs may correlate with a high PLP2+ Tumor EPCs score." (PMID 38482016, 2024). "In addition, the distribution of survival time showed that the higher PLP2+ Tumor EPCs score, the worse the prognosis." (PMID 38482016, 2024). "Therefore, to further discuss the role of the PLP2+ Tumor EPCs score in the tumor process, we analyzed the immune infiltration in two groups based on the PLP2+ Tumor EPCs score (high PLP2+ Tumor EPCs score group and low PLP2+ Tumor EPCs score group)." (PMID 38482016, 2024). "Consequently, the conclusion can be drawn that the low PLP2+ Tumor EPCs score group has a higher total of immune and stromal components, with a lower proportion of tumor cells, potentially correlating with better prognostic outcomes in this group." (PMID 38482016, 2024). "We have established an independent prognostic indicator—the PLP2+ Tumor EPCs score." (PMID 38482016, 2024). "Finally, the differences in different drug sensitivities in the high PLP2+ Tumor EPCs score group versus the low PLP2+ Tumor EPCs score group were shown by violin plots." (PMID 38482016, 2024). "PLP2 has been implicated in accelerating UCEC cell proliferation, the epithelial-mesenchymal transition (EMT) process, invasion, and metastasis, thereby promoting tumor progression." (PMID 38482016, 2024). "In addition, we also analyzed the survival of genes which constituted PLP2+ Tumor EPCs score, and the results showed that only four of them (SPIB, ATF6, PLAGL1, ERG) were statistically significant (P<0.05)." (PMID 38482016, 2024). "As could be seen from the figure, the tumor epithelial cell subgroup C3 PLP2+ Tumor EPCs had the highest expression on the CD99 signaling pathway." (PMID 38482016, 2024). "Combined with the previous experimental results in this paper, it could be concluded that the epithelial cell subgroup C3 PLP2+ Tumor EPCs was an important subgroup of tumor epithelial cells." (PMID 38482016, 2024). "Stromal Score, Immune Score and EATIMATE Score of high PLP2+ Tumor EPCs score group and low PLP2+ Tumor EPCs score group were displayed, and it could be obtained that the results of Stromal Score Group were not statistically significant." (PMID 38482016, 2024). "Treatment with these EVs reduced tumor growth via regulation of the miR-765/PLP2 axis." (PMID 36498469, 2022). "Additionally, CD45RO-CD8+ T cell-derived exosomes release high level of miR-765, and limit the tumor-promoting effects of estrogen on UCEC via regulation of the miR-765/PLP2 axis." (PMID 33859750, 2021). "We found that PLP2 expression correlates with tumor progression and poor prognosis in MM." (PMID 32596309, 2020). "PLP2 mediates tumor proliferation, invasion, and metastasis via the p38/ERK pathway." (PMID 31803141, 2019). "Besides, as the extracellular matrix degradation is an important factor for tumor invasion and metastasis, we also evaluated the possible influence of PLP2 expression and cell-matrix interaction." (PMID 30373180, 2018). "Additionally, we identified an independent prognostic factor, the PLP2+ Tumor EPCs score." (PMID 38482016, 2024). "Additionally, PLP2 is known to enhance tumor sphere-forming ability and cell proliferation." (PMID 38482016, 2024). "Consequently, PLP2 can facilitate tumor burden and influence the prognostic impact on MM." (PMID 32596309, 2020). "In HPV+ and HPV- groups, the proportion of C0 TMPRSS2+ Tumor EPCs subgroup in HPV+ group was the highest, and C3 PLP2+ Tumor EPCs subgroup in HPV- group was the highest." (PMID 38482016, 2024).
tumor (continued). "high PLP2+ Tumor EPCs score group highly expressed ATF6, ELF1, ERG and PLAGL1 genes, while low PLP2+ Tumor EPCs score group highly expressed ATF5, TBX21, SPIB, LHX2 and JUND genes." (PMID 38482016, 2024). "A reduced PLP2 expression led to growth inhibition of B16BL6 cells in vivo and prevented detectable metastasis from primary tumor cells by decreasing fibronectin and laminin, and by reducing the migratory ability of B16BL6 cells." (PMID 35190586, 2022).
cancer (12 papers, 2012 to 2025). A tumor composed of atypical neoplastic, often pleomorphic cells that invade other tissues. "Due to this association and its increased expression, PLP2 in cancer cells can promote cell proliferation, adhesion and invasion." (PMID 36139188, 2022). "In addition, in the cancer cell line dataset, PLP2, a gene implicated in cancer cell proliferation and migration, is regulated by two distal enhancer sets validated through CRISPRi and H3K27ac ChIP‐seq data in K562 cell line." (PMID 40832731, 2025). "This study will provide evidence for targeting the CircRNA_2646/miR-124/PLP2 axis for cancer therapy." (PMID 33976115, 2021). "Secondly, although several molecular biology techniques were performed to delineate the functions of CircRNA_2646, miR-124, and PLP2 axis, more studies based on different cancers were needed to further investigate this regulatory axis." (PMID 33976115, 2021). "Thus, PLP2 may provide a new window to understand the cellular mechanism of cancer progression." (PMID 34555810, 2021). "Therefore, CircRNA_2646, miR-124, and PLP2 might be potential biomarkers in ESCC and could be promising therapeutic targets for cancer treatments." (PMID 33976115, 2021). "Notably, a negative correlation between the expression of miR-765 and PLP2 was corroborated in 15 cancer tissues (r = -0.7596, P < 0.01)." (PMID 33859750, 2021).
infection (8 papers, 2011 to 2025). The state of being infected such as from the introduction of a foreign agent such as serum, vaccine, antigenic substance or organism. "The patatin-like protein 2 (plp2) expression increases during CaLCV infection, but the mutation of the plp2 gene results in the accumulation of JA." (PMID 39409638, 2024). "PLP2 encodes a lipid acyl hydrolase that accumulates upon infection with CaLCuV, fungi and bacteria and negatively affects resistance to the last two types of pathogens." (PMID 21818318, 2011). "The fact that PRRSV expresses multiple versions of PLP2 through the nsp2TF products, which each may have particular functions that may play critical roles in the infection, makes mutation of the PLP2 sequence more impactful than in viruses that do not express these extra TF products such as EAV." (PMID 38096325, 2023). "Using structure-guided mutagenesis and reverse genetics methods for PRRSV, we demonstrate that specific PLP2 residues that are critically involved in substrate recognition are under selective pressure to revert to wild-type during infection." (PMID 38096325, 2023). "Future study will be directed to investigate detailed mechanisms by which the PRRSV PLP2 plays during infection." (PMID 31561412, 2019). "We next investigated whether the same mutation affects the PLP2 cis- or trans-cleavage activity, which can be important for the processing of PRRSV polyprotein nsp2-3 during infection." (PMID 31561412, 2019). "Therefore a tripartite complex containing TBK1/IRF3/PLP2 would exist in cells after infection of MHV-A59." (PMID 21364999, 2011). "Herein, during the entire infection period, stronger symptoms of PCD in the susceptible cultivar SC1 than its male parental, resistant cultivar CG was illustrated by continuously and differentially up-regulated expression of PCD-related genes, for example, PLP2." (PMID 28261248, 2017). "The data also establish a strong link of nsp2 to pro-inflammatory cytokine induction during infection that operates in a manner independent of PLP2 DUB activity." (PMID 31561412, 2019). "Intriguing enough, results of PLP2 overexpression system and MHV-A59 infection system proved that PLP2 formed an inactive complex with TBK1 and IRF3 in the cytoplasm and the presence of PLP2 stabilized the hypo-phosphorylated IRF3-TBK1 complex in a dose-dependent manner." (PMID 21364999, 2011). "The papain-like cysteine protease 2 (PLP2) within the N-terminus of the porcine reproductive and respiratory syndrome virus (PRRSV) nsp2 replicase protein specifies a deubiquitinating enzyme (DUB), but its biochemical properties and the role in infection have remained poorly defined." (PMID 31561412, 2019).
PLP2 also shares sentences with these, for which no sentence is quoted: COVID-19 (2 papers); glioblastoma (2); leukemia (2); viral infection (2); acute lymphoblastic leukemia (1); brain tumour (1); cognitive disorder (1); colorectal cancer (1); esophageal squamous cell carcinoma (1); lung squamous cell carcinoma (1); Multiple Myeloma (1); myelodysplastic syndrome (1); renal cell carcinoma (1); skin cancer (1); smoldering multiple myeloma (1); triple-negative breast carcinoma (1).